PPARG (peroxisome proliferator activated receptor gamma)
Diseases named in the same sentence as PPARG in open-access papers (continued):
Sharing a sentence is not in itself a finding about the gene and the disease.
renal failure (7 papers, 2011 to 2024). "The increase of PPARg in this category of organs suggests a role of lipidic metabolic dysfunction in the development of kidney failure after a severe ischemic damage." (PMID 38503767, 2024). "Recently, a cluster of different papers linked PPARγ signaling with another superfamily, the transforming growth factor beta (TGFβ), and its receptors, all of which play a major role in PAH and kidney failure." (PMID 34638771, 2021).
allergic rhinitis (6 papers, 2005 to 2025). Inflammation of the nasal mucous membranes caused by an IgE-mediated response to external allergens. "In line with the importance of PPARγ in atopic diseases, another study suggested PPARγ activation as a potential therapeutic option for the treatment of allergic rhinitis." (PMID 36552866, 2022). "Of the several FA receptors, we focused on PPARγ because administration of a PPARγ agonist has been shown to inhibit allergic rhinitis by suppressing mast cell functions." (PMID 31766714, 2019). "The epithelial PPARγ immunoreactivity was similar in nasal biopsies from patients with allergic rhinitis and healthy volunteers, but was lower in polyps and further decreased after treatment with fluticasone." (PMID 16271155, 2005). "Therefore, an increased expression of PPARγ could have been expected in conjunction with the increased amount of inflammatory cells seen during symptomatic allergic rhinitis." (PMID 16271155, 2005). "The down-regulation of PPARγ, in nasal polyposis but not in turbinates during symptomatic seasonal rhinitis, suggests that PPARγ might be of importance in long standing inflammations, causing polyps, whereas an eventual role in allergic rhinitis remains to be established." (PMID 16271155, 2005). "In the present study, a higher expression of PPARγ and CD25CD71 was demonstrated in peripheral blood mononuclear cells of patients with allergic rhinitis compared to children without AR." (PMID 35244877, 2022).
cerebral malaria (6 papers, 2008 to 2022). A sequestration of Plasmodium falciparum in the brain, which can cause coma and/or seizures. "This review focuses on the utility of PPARγ agonists as an adjunctive therapy for the treatment of cerebral malaria." (PMID 21772838, 2012). "The effects of PPARγ agonists in vivo have been tested in a mouse model of experimental cerebral malaria (P. berghei ANKA)." (PMID 21772838, 2012). "Several anti-inflammatory properties of relevance to cerebral malaria pathology have been ascribed to PPARγ agonists." (PMID 21772838, 2012). "This review will focus on the utility of PPARγ agonists as an adjunctive therapy for the treatment of cerebral malaria." (PMID 21772838, 2012). "Findings from experimental CNS injury and disease models that demonstrate the potential for PPARγ agonists as an adjunctive therapy for cerebral malaria are also discussed." (PMID 21772838, 2012). "Relevant to cerebral malaria pathology, PPARγ is expressed not only in immune cells and in peripheral organs, but also in the CNS (microglia, astrocytes, perivascular macrophages, oligodendrocytes, and neurons) and in human brain microvascular endothelial cells." (PMID 21772838, 2012). "We will also summarize data on additional mechanisms of action attributed to PPARγ agonists that may be of benefit in cerebral malaria." (PMID 21772838, 2012). "Data on the anti-inflammatory and neuroprotective properties of PPARγ agonists in models of neuroinflammatory and neurodegenerative disease states may give us an insight into how PPARγ agonist could function in cerebral malaria." (PMID 21772838, 2012). "Thus, the anti-inflammatory properties of PPARγ agonists may be their most important quality when it comes to the treatment of cerebral malaria." (PMID 21772838, 2012). "However, whether PPARγ activation following the onset of cerebral malaria (once the inflammatory cascade has begun) will be protective is an open question." (PMID 21772838, 2012). "However, it is unknown whether the regenerative effects seen with long-term PPARγ agonist use in chronic CNS disease will also be obvious with a short treatment course, as would be administered in cerebral malaria." (PMID 21772838, 2012).
cholestasis (6 papers, 2014 to 2026). Impairment of the bile flow caused by obstruction within the liver, or outside the liver in the bile duct system. "Here, we investigated the effects of PPARγ agonism in a selective bile duct ligation (sBDL) model that reproduces key features of segmental cholestasis and the propagation of fibro-inflammatory signaling beyond the primary site of injury." (PMID 42034843, 2026). "PPARα and PPARγ have been reported to have protective effects in cholestasis by regulating bile acid metabolism in hepatocytes." (PMID 34776958, 2021).
chronic granulomatous disease (6 papers, 2013 to 2022). Chronic granulomatous disease (CGD) is a rare primary immunodeficiency, mainly affecting phagocytes, which is characterized by an increased susceptibility to severe and recurrent bacterial and fungal infections, along with the development of granulomas. "Treatment with the PPARγ agonist pioglitazone in a mouse model of chronic granulomatous disease (CGD; NADPH deficiency) with S. aureus infection restored reactive oxygen species (ROS) production by mitochondria in blood monocytes and tissue macrophages." (PMID 30897154, 2019). "PPARγ's anti-inflammatory function is also prominent in chronic granulomatous disease (CGD), an inherited disorder in which phagocytes' defective ability to kill certain infectious pathogens results in chronic and recurrent infections and inflammation." (PMID 27774097, 2016).
helminth infection (6 papers, 2018 to 2025). "We further determined the impact of helminth infection on the expression of PPARγ and found that H. polygyrus infection significantly decreased the HFD-induced upregulation of PPARγ in obese mice." (PMID 29545532, 2018). "Hence, PPARG was suggested as a factor that drives type 2 responses in worm infection." (PMID 29703268, 2018). "Helminth infection also significantly lowered the lipid accumulation in liver, which may attribute to the significant up-regulated expression levels of apolipoprotein E (ApoE) and down-regulated expression of peroxisome proliferator-activated receptor-gamma (PPAR-γ) and lipoprotein lipase (LPL)." (PMID 40708918, 2025). "To determine the mechanism by which helminth infection may alter HFD-induced body weight gain, we analyzed gene expression of key regulators mediating lipid metabolism in gonadal fat, including leptin, C/EBPα, and PPARγ." (PMID 29545532, 2018).
hemangioma (6 papers, 2016 to 2023). A benign vascular lesion characterized by the formation of capillary-sized or cavernous vascular channels. "Researchers have performed quantitative studies to investigate the role of “pro-adipogenic” genes (such as PPARγ) in hemangioma-genesis, proliferation to involution, and their interaction with propranolol, a beta-blocker used in the treatment of IH29." (PMID 27786256, 2016). "While treatment of hemangioma stem cells from infantile hemangiomas with IGF-1 positively influenced adipogenesis and expression of PPARγ, inhibition of IGF-1 receptor caused suppression of signals from C/EBPα, C/EBPβ and PPARγ." (PMID 32471255, 2020). "Also, overexpression of the PPARG gene enhanced and accelerated the adipogenic differentiation of hemangioma-derived mesenchymal stem cells (Hem-MSCs)." (PMID 30656515, 2019).
hypothyroidism (6 papers, 2020 to 2025). Abnormally low levels of thyroid hormone. "Moderate I2 concentrations prevented the increase in insulin and GLUT4 expression caused by hypothyroidism and retained the PPARG amount (2.1 + 0.07)." (PMID 37834351, 2023). "In MMI + H-I2, hypothyroidism was avoided, but pancreatic alterations and low PPARG expression remained." (PMID 37834351, 2023). "After PPI network construction, the top five hub genes associated with hypothyroidism were extracted, including ALB, MAPK1, SPP1, PPARG, and MIF, whereas those associated with hyperthyroidism were ALB, FCGR2B, CD44, LCN2, and CD74." (PMID 32500465, 2020). "The top five hub genes associated with hypothyroidism are ALB, MAPK1, SPP1, PPARG, and MIF, whereas those associated with hyperthyroidism are ALB, FCGR2B, CD44, LCN2, and CD74." (PMID 32500465, 2020). "PPARγ expression, as a master regulator of brown adipocytes’ structure and function, is not affected, while the expression of Pex 16, peroxin, which is a direct and functional PPARγ target gene, is strongly affected by hypothyroidism." (PMID 34571897, 2021). "In such a setting, our results suggest that in hypothyroidism, the regulation of peroxisomal biogenesis in brown adipocytes may be a result of mutual action of both PPARα and PPARγ." (PMID 34571897, 2021). "We examined the efficacy of Nrf2/HO-1 signaling and PPARγ in defining the molecular mechanism controlling the protective impact of ELT and HSP on CBZ-induced hypothyroidism in rats." (PMID 38745206, 2024).
intrahepatic cholestasis (6 papers, 2014 to 2025). A cholestasis characterized by impairment of the bile flow caused by obstruction located in the liver. "Several studies have proposed that the PPARγ agonist troglitazone induces intrahepatic cholestasis via the inhibition of ABCB11, potentially contributing to hepatotoxicity." (PMID 24799887, 2014). "Vincamine alleviated hepatic dysfunction during ANIT-induced intrahepatic cholestasis through its anti-inflammatory and antioxidant efficacies by the modulation of NF-kB/PDGF/klf6/PPARγ and PI3K/Akt pathways." (PMID 38761209, 2024).
keloid (6 papers, 2017 to 2022). An irregularly shaped, elevated mark on the skin caused by deposits of excessive amounts of collagen during wound healing. "PPAR and axon guidance pathways might be inhibited in keloid lesions because of the downregulated expression of PPARγ and Slit2, respectively." (PMID 35709140, 2022). "Furthermore, AA also suppressed expression of plasminogen activator inhibitor-1 (PAI-1) and collagen in TGF-β1-induced keloid fibroblasts by activating Peroxisome proliferator-activated receptor gamma (PPAR-γ)." (PMID 30233358, 2018). "PPARGC1A, PPARG, PLIN1, LPL, ABHD5, lncRNA PART1, lncRNA ENTPD3-AS1 in trunk keloid and DGAT2 in ear keloid showed decreased trend under paired comparation." (PMID 35677827, 2022).
liver cirrhosis (6 papers, 2014 to 2025). "This, in turn, affects a range of signal transduction-related proteins like CREB, LSD1, PPARγ, mTOR, and PRAS40, all of which are associated with liver cirrhosis." (PMID 38429802, 2024). "Hepatic PEDF and PPARγ are intrinsic protectors against liver cirrhosis." (PMID 27384427, 2016). "Not only are the results of this study in line with our previous finding but they also support the proposition that PEDF may protect individuals from liver cirrhosis by maintaining PPARγ levels in HSCs." (PMID 24763086, 2014).
malnutrition (6 papers, 2013 to 2022). Inadequate nutrition resulting from poor diet, malabsorption, or abnormal nutrient distribution. "PPARγ appears to be upregulated in malnutrition and fasting, contributing to the increased marrow adiposity seen with malnutrition." (PMID 31717370, 2019). "Despite we found a decrease in the gene expression of Pparγ, opposite results after the exposure to undernutrition and similar results after malnutrition during early development have been documented." (PMID 28082878, 2016). "Indeed, malnutrition during perinatal life could trigger changes in DNA methylation and in histone acetylation/methylation, causing transcriptional changes of key factors involved in adipogenesis (C/EBPα, PPARγ)." (PMID 27011203, 2016). "The loss of PPARγ enhanced the magnitude of antigen-specific recall responses to EAEC in nourished mice, whereas malnutrition abrogated responsiveness to antigens or to the mitogen ConA regardless of genotype." (PMID 23469071, 2013). "A previous study in rats also demonstrated that maternal malnutrition leads to alterations in PPAR gene expression (PPARα and PPARγ) in the offspring at 18 months of age." (PMID 25158235, 2014).
oral cancer (6 papers, 2015 to 2024). "Bexarotene might be effective in patients with high risk scores, and its anti-HNSCC efficacy was evidenced by targeting the PPARγ/RXRα heterodimer oral cancer preclinical test." (PMID 36105083, 2022). "The results of our study demonstrated lower expression of PRODH/POX and PPARγ and higher expression of HIF-1α in oral cancer tissue in comparison to normal tissue in all study participants, although the obtained values differed significantly between individual patients." (PMID 31935820, 2020). "Previously, we found a set of retinoid signaling related genes, including ADHFE1, ALDH1A2, CRBP1, PAX9, GDF10, TGFBR3, and PPARγ were frequently hypermethylated and downregulated in OSCC patient samples, suggesting the severe molecular defects in RA metabolism in oral cancer." (PMID 32238162, 2020). "Although microarray data did not demonstrate significant differential expression of PPARγ in rat oral cancers, KEGG analysis of microarray data from these samples did identify statistically significant differential expression of PPARγ-associated signaling pathways in OSCC." (PMID 26516762, 2015). "The expression levels of FABP3, PPARG, PLIN5, ACACB, and PDK4 in oral cancer samples were significantly lower than those in adjacent normal samples (all p < 0.05) and then were included in the prognosis analysis." (PMID 36478991, 2022).
osteopetrosis (6 papers, 2015 to 2024). Osteopetrosis, also known as marble bone disease, is a descriptive term that refers to a group of rare, heritable disorders of the skeleton characterized by increased bone density on radiographs. "Loss of function by targeted PPARγ deletion impairs osteoclast differentiation and bone resorption, resulting in osteopetrosis." (PMID 39278948, 2024). "Accordingly, Pparγ‐knockout mice exhibit severe osteopetrosis underlining the importance of osteoclasts for physiological bone turnover." (PMID 37710406, 2023). "Genetically, the loss of PPARγ function in mouse hematopoietic lineages causes osteoclast defects, which present as osteopetrosis." (PMID 29100332, 2017).
pancreatitis (6 papers, 2008 to 2024). Inflammation of the pancreas. "Cer-pancreatitis significantly increased PPARγ levels compared to control levels (transcript and protein levels by 1.3 and 1.4-fold, respectively)." (PMID 38927047, 2024). "As in the stomach, PPARγ activity is beneficial in various animal models of pancreatitis, reducing inflammation, restoring exocrine pancreas functions, and limiting chronic pancreatitis development." (PMID 19125181, 2008). "Irisin addition in the cer-pancreatitis state resulted in a significant down-regulation of the PPARγ-PGC1α-FNDC5 axis, PPARγ nucleus-translocation and inflammatory state (TNFα and IL-6) in parallel to diminished PL expression and secretion (in vitro and ex vivo models)." (PMID 38927047, 2024). "Irisin’s pro-survival effect under cer-pancreatitis state was abolished under PPARγ inhibition." (PMID 38927047, 2024). "The beneficial role of PPARγ activation in inflammatory diseases of the digestive tract may not be limited to the intestine, but seems to extend to gastritis and pancreatitis, an inflammation of the gastric mucosa and pancreas, respectively." (PMID 19125181, 2008).
periodontal disease (6 papers, 2017 to 2025). "Pathogenic bone resorption occurring in periodontal disease is known to be produced by inflammation, PPARγ activation can downregulate the bone resorption mediated by RANKL-dependent osteoclastogenesis." (PMID 28678155, 2017). "The interaction between PPARγ gene polymorphism with periodontal disease has been studied in some papers without a clear conclusion." (PMID 28678155, 2017).
Peritoneal Fibrosis (6 papers, 2015 to 2025). Disorder characterized by a wide range of structural changes in PERITONEUM, resulting from fibrogenic or inflammatory processes. "Furthermore, the potentials of rosiglitazone and 15d-PGJ2, as well as other PPARγ agonists, in treating PD-associated peritoneal fibrosis deserve further explorations through large-scale clinical trials." (PMID 35380292, 2022). "To explore the role of PPARγ in modulating peritoneal fibrosis (PF) development, we first established the rat PF model with the combination of high glucose and lipopolysaccharide (LPS) treatments as introduced in methods." (PMID 35380292, 2022). "To further explore the role of PPARγ in regulating the development of peritoneal fibrosis (PF), we constructed PPARγ overexpression vector and injected it into PF rats." (PMID 35380292, 2022). "PPARγ inhibited high glucose-induced peritoneal fibrosis progression through elevating GLUT1 expression and repressing peritoneal mesothelial cell proliferation." (PMID 35380292, 2022). "Besides, PPARγ was regarded as a potential target for peritoneal fibrosis in either normoxic or hypoxic conditions, and the key step to abolish the changes of adhesion phenotype in fibroblast was to elevate PPARγ level." (PMID 35308169, 2022). "In terms of PD-induced peritoneal fibrosis, previous reports using both animal and cellular models demonstrated the effective suppression of PD/high glucose-induced PF development by treatments with PPARγ agonists such as Telmisartan and pioglitazone." (PMID 35380292, 2022). "In the present study, we reported that PPARγ could substantially modulate peritoneal fibrosis pathogenesis in rat model." (PMID 35380292, 2022). "While limited studies exist on the role of Parvibacter in kidney disease, one study revealed that it may prevent peritoneal fibrosis induced by peritoneal dialysis in end-stage kidney disease by enhancing butyrate production, activating PPARγ and inhibiting NF-κB-mediated inflammatory pathways." (PMID 40171160, 2025). "For more understanding of the molecular mechanisms, we then assessed the interaction between PPARγ and GLUT1 expression in peritoneal fibrosis progression." (PMID 35380292, 2022).
prostatic intraepithelial neoplasia (6 papers, 2013 to 2023). "Decreased PPARγ signaling due to HFD was recently associated with reduced androgen signaling and low grade PIN (Prostatic Intraepithelial Neoplasia); however, PPARγ's status has not been previously investigated in a context of marrow adiposity and metastatic prostate cancer." (PMID 24240026, 2013).
pulmonary alveolar proteinosis (6 papers, 2012 to 2022). A rare lung disorder characterized by the filling of the pulmonary alveoli with proteinaceous material which stains positive with periodic acid-Schiff stain. "In fact, blockade of GM-CSF-initiated signaling or deletion of the PPARγ-encoding gene PPARG leads to functionally defective A-MØ and the onset of pulmonary alveolar proteinosis." (PMID 29434585, 2018). "The deficiency in GM‐CSF‐dependent PPARγ‐activity in AM leads to pulmonary alveolar proteinosis (PAP)." (PMID 34358410, 2021). "In fact, PPARγ expression in A-MØ is lost in GM-CSF-deficient mice and in patients with pulmonary alveolar proteinosis (PAP), a pathology derived from a defective expression or activity of GM-CSF and associated with suppressed activin A expression." (PMID 29434585, 2018). "Accordingly, absence of PPARγ, GM-CSF, or 1 of the 2 GM-CSF receptor subunits (CSF2R α and β) in mice results in abrogated alveolar macrophage development and pulmonary alveolar proteinosis (PAP)." (PMID 35393945, 2022).